HTRA4 (HtrA serine peptidase 4)
Description:
Serine protease.
Synonyms: FLJ90724
Tractability: Antibody: UniProt places it where antibodies can reach, with medium confidence; UniProt predicts a signal peptide or a membrane-spanning region; its Gene Ontology location is reachable by antibodies, with medium confidence.
Gene: Protein-coding gene on chromosome 8 (38,974,228 to 38,988,663, forward strand). Ensembl gene ENSG00000169495.
Subcellular location: Secreted
Gene Ontology:
Molecular function: endopeptidase activity; identical protein binding; protein binding; serine-type endopeptidase activity
Biological process: proteolysis; negative regulation of transforming growth factor beta receptor signaling pathway; positive regulation of apoptotic process; programmed cell death
Cellular component: extracellular region
Genetic constraint (gnomAD): Loss-of-function variants: 40 observed, 34.63 expected, observed/expected ratio (o/e) 1.15, 90% interval 0.9 to 1.5. The upper end of that interval is the gene's LOEUF score, 1.5, which puts it in group 6 of 6, group 1 being the genes least tolerant of losing a copy. Missense variants: 582 observed, 555.91 expected, observed/expected ratio (o/e) 1.05, 90% interval 0.98 to 1.12. Synonymous variants: 249 observed, 233.84 expected, observed/expected ratio (o/e) 1.06, 90% interval 0.96 to 1.18.
Homologues: Orthologues: chimpanzee HTRA4 (99% identical), macaque HTRA4 (90% identical), rabbit HTRA4 (69% identical), dog HTRA4 (67% identical), mouse Htra4 (67% identical), rat Htra4 (67% identical), tropical clawed frog htra4 (53% identical), zebrafish htra4 (51% identical). Paralogues in human: HTRA1 (51% identical), HTRA3 (48% identical), HTRA2 (36% identical).
Diseases named in the same sentence as HTRA4 in open-access papers:
HTRA4 is named in the same sentence as 19 diseases in open-access papers, as found by Europe PMC text mining. Sharing a sentence is not in itself a finding about the gene and the disease. The quoted sentences say what the papers report.
preeclampsia (10 papers, 2019 to 2025). Preeclampsia is a hypertensive disorder of pregnancy that is characterized by new-onset hypertension with proteinuria presenting after 20 weeks of gestation, and depending on mild or severe forms may initially present with severe headache, visual disturbances, and hyperreflexia. "Human high-temperature requirement serine peptidase A4 (HTRA4) is a placental-specific protease emerging as a pathogenic factor and biomarker in preeclampsia." (PMID 38099221, 2023). "Taken together, these findings suggest that excessive placental production HtrA4 may be more associated with early-onset preeclampsia." (PMID 34639128, 2021). "Several studies have linked abnormal placental expression of HtrA4 to early-onset preeclampsia." (PMID 34639128, 2021). "Archetypal targets of the R364X mutant compared to the WT cells are the metallothionein complex of genes on chromosome 16 (from 2- to 5.76-fold), LGALS1 (x4.48-fold), or HTRA4 (x22.81), genes known to be connected with preeclampsia." (PMID 38439971, 2024). "This study demonstrated that the combination of serum HtrA4 levels and uterine artery Doppler in the first-trimester was effective for predicting preeclampsia." (PMID 37217518, 2023). "HtrA4 was overexpressed, particularly in syncytiotrophoblast in preeclamptic placentas, and maternal serum HtrA4 levels were elevated in preeclampsia gestations." (PMID 37217518, 2023). "High-temperature requirement factor A4 (HtrA4) is the placenta-specific serine proteases which were detected in the maternal circulation of patients diagnosed with preeclampsia." (PMID 37217518, 2023). "Further elucidating the upstream regulation and precise molecular interactions of HTRA4 in placental cells will provide greater insight into its role as a candidate driver and biomarker in preeclampsia pathogenesis." (PMID 38099221, 2023). "The mean serum HtrA4 levels were higher in the preeclampsia group than the control group (9.4 ± 3.9 vs 4.6 ± 2.2 ng/ml, p < 0.001)." (PMID 37217518, 2023). "This study found that serum HtrA4 levels were elevated before the onset of preeclampsia, making it one of the possible biomarkers that can predict preeclampsia." (PMID 37217518, 2023). "This study found that the combination of serum HtrA4 levels and uterine artery Doppler in the first trimester was effective for predicting preeclampsia." (PMID 37217518, 2023). "Sensitivity and specificity of serum HtrA4 levels in the first trimester to predict preeclampsia in this study were 76.5% and 90.7%, respectively." (PMID 37217518, 2023). "The objective of this study was to investigate the predictive value of serum high-temperature requirement protease A4 (HtrA4) and the first-trimester uterine artery in predicting preeclampsia in singleton pregnancy." (PMID 37217518, 2023). "The strength of this study is that it is the first prospective study using the first-trimester serum HtrA4 levels combined with the UtA-PI to predict preeclampsia." (PMID 37217518, 2023). "Serum HtrA4 levels and transabdominal uterine artery Doppler ultrasound were performed to evaluate this combination for calculating the predictive value of preeclampsia." (PMID 37217518, 2023). "The serum HtrA4 level was higher in the preeclampsia group than in the control group (9.4 vs 4.6 ng/ml)." (PMID 37217518, 2023). "A combination of serum HtrA4 levels and uterine artery Doppler in the first trimester had good sensitivity for predicting preeclampsia." (PMID 37217518, 2023). "Mean serum HtrA4 levels were higher in the preeclampsia group than in the control group (9.4 ± 3.9 vs 4.6 ± 2.2 ng/ml, p < 0.001)." (PMID 37217518, 2023). "Collectively, these data point to HtrA4 as a potential contributor of endothelial dysfunction in early-onset preeclampsia." (PMID 34639128, 2021). "The involvement of HtrA4 in pregnancy complications such as preeclampsia will be further discussed in a later part of this review." (PMID 34639128, 2021).
preeclampsia (continued). "To date, we and others have reported that placental expression of HtrA4 is significantly increased in preeclampsia, especially in the early-onset subtype at the time of disease presentation compared to normal pregnancies." (PMID 34257367, 2021). "HTRA4 mRNA is subsequently confirmed to be significantly upregulated in the placenta of early-onset preeclampsia, and HtrA4 serum levels are likewise highly elevated at the time of disease presentation." (PMID 34639128, 2021). "Gene expression analyses consistently show a significant upregulation of HTRA4 in severe preeclampsia compared to their gestational-matched controls." (PMID 34639128, 2021). "High temperature requirement factor A 4 (HtrA4) is a placental-specific protease, expressed by various trophoblasts including syncytiotrophoblast, and significantly elevated in preeclampsia at disease presentation." (PMID 34257367, 2021). "The sensitivity, specificity, positive predictive value (PPV), and negative predictive value (NPV) were 76.5%, 90.7%, 45.6%, and 97.4%, respectively, when using serum HtrA4 levels above 1.8 multiples of the median for the gestational age as a cut-off value for predicting preeclampsia." (PMID 37217518, 2023). "Thus, the aim of this study was to investigate the role of first-trimester serum HtrA4 levels combined with UtA-PI in predicting preeclampsia in singleton pregnancy." (PMID 37217518, 2023). "These combined findings indicate that HTRA4 may contribute to insufficient trophoblast invasion and placental dysfunction in preeclampsia." (PMID 38099221, 2023). "Since placental HtrA4 is secreted into the maternal blood, elevated circulating HtrA4 may adversely impact the maternal vasculature and contribute to systemic endothelial dysfunction, which is often observed in early-onset preeclampsia." (PMID 34639128, 2021). "Both proteases, HTRA1 and HTRA4, are elevated in the placenta of preeclampsia patients." (PMID 34884497, 2021). "These seemingly conflicting reports suggest that HtrA4 expression may differ between different subtypes of preeclampsia, and that significant elevation of HtrA4 is likely a distinct characteristic of early-onset preeclampsia." (PMID 34639128, 2021). "On the other hand, excessive production of HtrA4 may adversely impact the placenta and maternal endothelium, contributing to pregnancy complications such as preeclampsia." (PMID 34639128, 2021). "Furthermore, HtrA4 levels in the maternal circulation are significantly elevated in the third trimester at the diagnosis of early-onset preeclampsia, and the circulating HtrA4 levels positively correlate to the severity of preeclampsia." (PMID 34639128, 2021). "Mechanistically, HTRA4 has been shown to degrade extracellular matrix proteins like fibronectin and cleave endothelial junction protein vascular endothelial cadherin—effects that may impair trophoblast invasion and maternal vascular integrity in preeclampsia." (PMID 38099221, 2023). "In particular, HtrA4 upregulates the expression of pro-inflammatory factors IL6, PTGS2 and IL1B to a level equivalent to that observed in early-onset preeclampsia." (PMID 34639128, 2021). "On the other hand, THBS1, which is closely involved in endothelial adhesion, motility and proliferation, is significantly downregulated by HtrA4, consistent with THBS1 being lower in women with severe preeclampsia." (PMID 34639128, 2021). "A combination of serum HtrA4 levels and UtA-PI > 95th percentile yielded sensitivity, specificity, PPV, and NPV of 79.4%, 86.1%, 37% and 97.6%, respectively, for the prediction of preeclampsia." (PMID 37217518, 2023). "Proposed mechanisms of disrupted endothelial barrier integrity include the release of placenta-derived HtrA serine peptidase 4 (HTRA4), which is increased in serum from patients with early-onset preeclampsia and responsible for cleaving VE-cadherin, an endothelial junctional protein." (PMID 34831277, 2021).
endothelial dysfunction (4 papers, 2016 to 2023). In vascular diseases, endothelial dysfunction is a systemic pathological state of the endothelium (the inner lining of blood vessels) and can be broadly defined as an imbalance between vasodilating and vasoconstricting substances produced by (or acting on) the endothelium. "Overall, our study suggests that high levels of placental-derived HtrA4 that is circulating in early-onset PE women is a potential causal factor of endothelial dysfunction." (PMID 27780539, 2016). "The high level of placental-derived HtrA4 is a possible causal factor of endothelial dysfunction." (PMID 37217518, 2023). "In addition, the increased placental-derived HTRA4 in plasma circulation is a potential cause of endothelial dysfunction, altering a series of endothelial genes related to inflammation, vascular activity, angiogenesis, cell adhesion, platelet activation, and coagulation." (PMID 38048229, 2023). "Indeed, recombinant human HtrA4 can cleave the main surface receptor for vascular endothelial growth factor (VEGF)-A which is also known as kinase insert domain receptor (KDR), causing an inhibition of VEGF-A action and endothelial dysfunction." (PMID 34639128, 2021). "This suggest that endothelial genes in this group may not be the major targets of HtrA4 action, and other placental-derived factors may be responsible for their dysregulation and contribute to the endothelial dysfunction." (PMID 27780539, 2016).
breast carcinoma (3 papers, 2019 to 2024). "In this work, using lung and breast cancer cell lines, we showed for the first time that the full-length HtrA4 and its N-terminally deleted variant promote cancer cell death induced by chemotherapeutic drugs by enhancing apoptosis." (PMID 31546993, 2019). "A similar cytoplasmic localization was found in the MCF7, MDA-MB231, and T47D breast cancer cells, which contained endogenous HtrA4 mainly in a truncated form." (PMID 31546993, 2019). "Specifically, it was shown that HtrA4 is upregulated in glioblastoma multiforme compared to control brain from epilepsy patients and in breast carcinoma compared to normal breast samples." (PMID 31546993, 2019). "To confirm these conclusions, we used the lung and breast cancer cells with suppression of the HtrA4 gene by shRNA." (PMID 31546993, 2019). "We found that indeed, HtrA4 was secreted into the medium by the cultured MCF7 breast cancer cells, which contained a relatively high level of endogenous HtrA4." (PMID 31546993, 2019). "As shown by the MTT and SRB tests, HtrA4 silencing significantly increased the viability of drug-treated lung and breast cancer cells in comparison to the control cells." (PMID 31546993, 2019). "A similar cytoplasmic localization was found in the MCF7, MDA-MB231, and T47D breast cancer cells, which contain endogenous, truncated HtrA4." (PMID 31546993, 2019). "Additionally, we modulated HtrA4 production in breast cancer cells (MCF7) that contained a high level of endogenous HtrA4." (PMID 31546993, 2019). "To date, no studies have reported HTRA4 expression in primary tumour samples, although a previous review has suggested that HtrA4 may be dysregulated in some cancers such as glioblastoma, breast carcinoma, and primary prostate carcinoma." (PMID 34639128, 2021).
fetal growth restriction (2 papers, 2015 to 2023). A fetus that does not grow beyond the 10th percentile of conventionally accepted weight for gestational age. "This suggests that the increased HTRA4 expression might be related to the pre-eclampsia phenotype associated with preterm delivery and fetal growth restriction." (PMID 26388242, 2015). "This provides support for the hypothesis according to which elevated HTRA4 expression may be related to the early-onset pre-eclampsia associated with fetal growth restriction." (PMID 26388242, 2015). "The relative risk was not significant for preterm delivery, gestational diabetes mellitus, and fetal growth restriction after using the combination of serum HtrA4 levels and uterine artery Doppler in the first trimester." (PMID 37217518, 2023).
glioblastoma (2 papers, 2019 to 2021). The most malignant astrocytic tumor (WHO grade IV). "Moreover, it was indicated that the allelic ratio of HtrA4 is lower in glioblastoma compared to normal DNA control." (PMID 31546993, 2019).
lung carcinoma (2 papers, 2019 to 2023). "A recent study suggested that the expression of HTRA4 enhances the effect of chemotherapy in breast and lung cancer cell lines." (PMID 36835239, 2023). "We found that exogenous production of the HtrA4 and ΔN-HtrA4 proteins significantly reduced clonogenic potential as well as ability to migrate of etoposide-exposed lung cancer cells in comparison to controls." (PMID 31546993, 2019). "To confirm that HtrA4 promotes cell death, we used a reverse, complementary approach and downregulated the HtrA4 expression by shRNA in the A549 lung cancer cells." (PMID 31546993, 2019).
prostate carcinoma (2 papers, 2019 to 2021). A carcinoma that arises from epithelial cells of the prostate gland. "On the other hand, meta-analyses of available microarray data showed changed levels of the HtrA4 gene expression in brain tumors and the breast and prostate cancers in comparison to normal tissues, which suggests HtrA4 connection with carcinogenesis." (PMID 31546993, 2019). "The meta-analyses of microarray assays revealed that the HtrA4 level is changed in brain tumors and breast and prostate cancers, which suggests its involvement in oncogenesis." (PMID 31546993, 2019). "Moreover, the changed levels of HtrA4 expression were observed in brain tumors and the breast and prostate cancers in comparison to the normal tissues, which suggests HtrA4 involvement in oncogenesis." (PMID 31546993, 2019).
abortion (1 paper, 2023). the ending of pregnancy by removing a fetus or embryo before it can survive outside the uterus. "Therefore, we aimed to investigate the changes in serum HtrA4 levels after abortion and evaluate their correlation with non-pregnancy status using the HtrA4 ELISA kit." (PMID 37296580, 2023).
diabetes (1 paper, 2023). "The results for the predictive values of HtrA4 could have been stronger if pregnancies with chronic hypertension and overt diabetes were excluded." (PMID 37217518, 2023).
hyperlipidemia (1 paper, 2022). "Cluster 1 represents a distinct population of cells expressing genes involved in inflammation (Ifi27l2a), hyperlipidemia (Gata4), VSMC phenotypic modulation (Meox1), calcification and bone formation (Htra4, Meox1)." (PMID 35163719, 2022).
Insulin resistance (1 paper, 2019). Increased resistance towards insulin, that is, diminished effectiveness of insulin in reducing blood glucose levels. "Two more genes supporting these mechanisms of insulin resistance were found here among the most overexpressed genes: HTRA4 (IGF binding domain containing protein, fold-change = 7.33) and LEP (leptin, fold-change = 4.89)." (PMID 31998361, 2019).
pregnancy disorder (1 paper, 2014). A disorder that is related to pregnancy. "Since HtrA1, HtrA3 and HtrA4 share identical domain organization, our results establish important foundations for developing potential therapeutics to target these HtrA proteins specifically for the treatment of a number of diseases, including cancer and pregnancy disorders." (PMID 25248123, 2014).
tumor (6 papers, 2015 to 2023). "The structure of the HtrA4 domain is highly comparable to that of HtrA1 and HtrA3, and several publications have reported that the HtrA4 as a tumor suppressor is involved in oncogenesis." (PMID 37296580, 2023). "HTRA4 is thought to be involved in the modulation of apoptosis and chemotherapy-induced cytotoxicity with a tumor-suppressive role." (PMID 27385100, 2016). "The high similarity of the HtrA4 protein domain structure to that of HtrA1 and HtrA3 and implication of HtrA4 in oncogenesis suggested that it may function similarly to the HtrA1/3, which act as tumor suppressors and promote cell death." (PMID 31546993, 2019). "A number of fast evolving, placental genes show tumorigenic or tumor suppression activity (ADAM12, ADAMTS18, CAPN6, EGFL6, HTRA4, LIN28B) and others are involved in disorders associated with epithelial and connective tissues (FBN2) or have immune functions (IL1RL1, PRG2, SIGLEC6)." (PMID 26641094, 2015). "It is noteworthy that HtrA4 expression has not yet been reported in any primary tumour samples, suggesting an unlikely involvement of this HtrA in cancer." (PMID 34639128, 2021). "However, so far, HtrA4 expression has not been shown in any primary cancer cells or in vivo tumours." (PMID 34639128, 2021).